PIK3CA (phosphatidylinositol-4,5-bisphosphate 3-kinase catalytic subunit alpha)
Diseases named in the same sentence as PIK3CA in open-access papers (continued):
Sharing a sentence is not in itself a finding about the gene and the disease.
lymph node metastasis (32 papers, 2005 to 2025). "The relationships between PIK3CA mutations and age, sex, smoking status, histology and lymph node metastasis have been unclear up to now." (PMID 41153394, 2025). "The presence of PIK3CA mutations in primary tumors was significantly associated with lymph node metastasis in the primary setting, both when assessing nodal status as negative (pN0) versus positive (pN1-3), and the respective pN category (pN0-3)." (PMID 38822093, 2024). "On the other hand, there were statistically significant negative correlations between perineural invasion and phosphotidylinositol-4,5-biphosphate 3-kinase (PIK3CA) mutation (P = .043) and between lymph node metastasis and BRCA2 mutation (P = .009)." (PMID 37737217, 2023). "In one study, PIK3CA alteration was associated with lymph node metastasis, and PIK3CA mRNA was associated with the tumor stage." (PMID 36359251, 2022). "Among the 10 included studies which focused on PIK3CA mutation in NSCLC, more than half of them did not provide detailed information for us to calculate the relation of PIK3CA gene mutation with sex, age, lymph node metastasis, TNM stage, and smoking." (PMID 32908885, 2020). "Only lymph node metastasis status had an association with PIK3CA mutation (RR = 2.823; 95% CI: 1.128-7.065; P = 0.029)." (PMID 32908885, 2020). "Unfortunately, only lymph node metastasis status seemed to have a relation with PIK3CA mutation (RR = 2.823, 95% CI: 1.128-7.065, P = 0.029)." (PMID 32908885, 2020). "In matched archival samples, three primary tumors and the lymph node metastasis (29%) carried PIK3CA mutations." (PMID 30211312, 2018). "The authors used IHC for measurement of PIK3CA and reported that elevated PIK3CA expression associated with a poor prognosis including lymph node metastases." (PMID 24083111, 2013). "As for HNSCC, several reports have shown that EGFR copy number alterations are associated with a poor prognosis; it is also reported that PIK3CA copy number amplification is associated with lymph node metastasis." (PMID 22994622, 2012). "Interestingly, clinically-relevant genomic alterations of PIK3CA have been reported in some recurrent, metastatic cSCC and PIK3CA activating mutations have been detected in some cSCC lymph node metastases." (PMID 33808215, 2021). "According to the data provided by 3 included studies, we explored the association of PIK3CA gene expression with sex (male vs. female), age (≥65 vs. <65), differentiation (lower vs. higher), lymph node metastasis (+ vs. -), TNM stage (advanced vs. limited), and smoking history (yes vs. no)." (PMID 32908885, 2020). "Whether PIK3CA gene mutation has a significant relation with clinicopathological characteristics such as age, differentiation, and lymph node metastasis and whether it could affect the survival of NSCLC patients are unclear up to now." (PMID 32908885, 2020). "PIK3CA mutation may affect lymph node metastasis and serve as a promising prognostic factor, and smoking may be related with PIK3CA high expression in NSCLC patients." (PMID 32908885, 2020). "Based on the information reported by 10 included studies, we explored the association of PIK3CA gene mutation with the sex (male vs. female), age (≥60 vs. <60), lymph node metastasis (+ vs. -), TNM stage (advanced vs. limited), and smoking history (yes vs. no)." (PMID 32908885, 2020). "In conclusion, PIK3CA mutation might affect lymph node metastasis and serve as a promising prognostic factor, and smoking may be related with PIK3CA high expression in NSCLC patients." (PMID 32908885, 2020).
lymph node metastasis (continued). "Mutated genes associated with lymph node metastasis in the univariate analysis, including RET, ATM, PIK3CA, TERT, GGT1 and fusions, were incorporated to construct a gene signature model." (PMID 38886866, 2024). "Associations between PIK3CA or NRAS mutations and patient characteristics, such as age, gender, tumor location, histological type, tumor differentiation, invasion depth, lymph node metastasis, distant metastasis or TNM stage, were statistically insignificant." (PMID 26691448, 2015). "The results show that not only the patients with low miR-1 expression but also those with high PIK3CA expression had significantly higher incidences of lymph node metastases and recurrences in one year after surgery than other patients." (PMID 24949449, 2014). "In order to assess the independent associations between promoter methylation of these genes and PIK3CA amplification, smoking history, histologic type, and lymph node metastasis, we conducted multiple multivariable logistic regressions." (PMID 21507233, 2011). "Hypopharyngeal localization, positive PTEN expression, absence of PIK3CA (H1047R) mutation, and negative p-S6 (Ser235/236) showed an independent predictive value for lymph node metastasis." (PMID 27119232, 2016). "So, the expression levels of miR-1 and PIK3CA in NSCLC tissues may be useful for predicting lymph node metastasis and postoperative recurrence in patients with NSCLC." (PMID 24949449, 2014). "(Log-rank test, p = 0.026) Copy number amplification of the PIK3CA gene is associated with poor prognosis in HNSCC patients without lymph node metastasis." (PMID 22994622, 2012). "However, when the patients with lymph node metastases were excluded from the population, a significant correlation was found between PIK3CA copy amplification and the time to relapse (log-rank test, p =0.026)." (PMID 22994622, 2012). "Kaplan-Meier survival analysis revealed that copy-number amplification of PIK3CA was markedly associated with cancer relapse in patients without lymph node metastasis." (PMID 22994622, 2012). "Copy number amplification of the PIK3CA gene is associated with poor prognosis in HNSCC patients without lymph node metastasis." (PMID 22994622, 2012). "Copy number amplification of the PIK3CA is associated with poor prognosis in HNSCC patients without lymph node metastasis." (PMID 22994622, 2012). "PIK3CA amplification has also been found to be associated with poor prognosis in HNSCC patients without lymph node metastasis, and therefore could be a potential prognostic marker." (PMID 38473941, 2024). "The negative association between PIK3CA mutations and lymph node metastasis may be explained by the fact that actionable mutations in PIK3CA display constitutive activation of Akt." (PMID 37195967, 2023). "Additionally, in the literature, no clear relationship between PIK3CA mutations and lymph node metastasis or histopathological diagnosis was observed." (PMID 33669698, 2021). "PIK3CA mutations were not correlated with clinicopathological characteristics, including age, gender, tobacco use, alcohol use, family cancer history, tumor location, pathologic stage, differentiation, lymph node metastasis, tumor embolus, local recurrence, and prognosis." (PMID 25054828, 2014).
lymph node metastasis (continued). "Significant relationships determined between KRAS exon 2 and mucinous morphology, PIK3CA and absence of perineural invasion, BRAF and tumor differentiation and localization, MSH3 and tumor diameter, and BRCA2 and absence of lymph node metastasis were findings that have contributed to the literature." (PMID 37737217, 2023). "Moreover, it was stated that the expression level of the PIK3CA, PIK3R1, PTEN, AKT1, mTOR genes does not depend on the patients’ age, lymph node metastases, ER, PR status and Ki-67 index." (PMID 33669698, 2021). "Finally, concerning lymph node metastases, CCNL1 and TP73L showed an increased frequency of gains (CCNL1: P=0.02; TP73L: P=0.05), while for SNO and PIK3CA no such correlation was observed." (PMID 15700036, 2005).
lymphatic malformation (30 papers, 2016 to 2025). Primary lymphedema is caused by anatomic or functional defects in the lymphatic system, resulting in chronic swelling of body parts and lymphatic-system malformation. "PIK3CA mutations were detected in 50% of children with lymphatic malformations, with the p.E542K variant being the most prevalent hotspot mutation." (PMID 41300578, 2025). "PIK3CA mutations were more frequently detected in isolated lymphatic malformations (63%) than in complex forms and were most commonly associated with truncal lesions." (PMID 41300578, 2025). "In summary, our findings confirm that PIK3CA mutations are common in lymphatic malformations and play a pivotal role in their pathogenesis." (PMID 41300578, 2025). "The results confirm the key role of PIK3CA mutations in lymphatic malformation pathogenesis and highlights the clinical importance of incorporating molecular diagnostics into routine evaluation." (PMID 41300578, 2025). "The second pathogenic PIK3CA gene variant, p.Gln546Lys, has been reported in a newborn who had lymphatic malformation of the tongue." (PMID 39872006, 2024). "All patients with geographic capillary malformation, histopathological lymphatic malformation or macrodactyly of the foot had PIK3CA variants." (PMID 37667289, 2023). "PIK3CA mutation was previously reported for venous and lymphatic malformations, and PI3K/Akt/mTOR pathway is a critical downstream target which exacerbates the lesion growth." (PMID 35844490, 2022). "PIK3CA mutations, on the other hand, are also detected in lesions of venous or lymphatic malformations." (PMID 35216474, 2022). "For instance, out of five patients with the mutation p.(Glu545Lys) in PIK3CA, two had an isolated venous malformation, one had a lymphatic malformation, one had a capillary–venous malformation, and another had a lymphatic–venous malformation." (PMID 33105631, 2020). "For example, mutations in the PIK3CA gene were found associated with the development of venous and lymphatic malformations or syndromes including these types of VA." (PMID 32488381, 2020). "More recently, the discovery of somatic activating mutations of PIK3CA gene in venous and lymphatic malformations has opened new perspectives for therapeutic options." (PMID 29352118, 2018). "This triggered a strong mTORC1 and S6Kinase activation, and treatment with the FDA-approved drug rapamycin (sirolimus), an mTORC1 inhibitor commonly used for the treatment of venous and lymphatic malformations caused by Pik3ca GOF mutations, improved lesion outcomes." (PMID 38747293, 2024). "Activating mutations in the PIK3CA gene are associated with lymphatic malformations (LMs)." (PMID 35763346, 2022). "In conclusion, our systematic data on a large cohort of patients with lymphatic malformations demonstrate that 75.5% of LMs, whether common, combined, or syndromic, are caused by somatic activating PIK3CA mutations." (PMID 34112235, 2021). "Beyond these multisystem disorders, mosaic mutations of PIK3CA have recently been identified in localized or focal forms of overgrowth with dysplasia including epidermal nevi, isolated macrodactyly, infiltrating lipomatosis, isolated lymphatic malformations, and, most recently, venous malformations." (PMID 27631024, 2016). "VEGF-C/VEGFR3 signaling was recently shown to promote the progression of PIK3CA-induced lymphatic malformations." (PMID 37842094, 2023). "On the other hand, the PIK3CA/Akt/mTOR pathway, as PIKopathy, induces slow-flow vascular malformations, such as venous or lymphatic malformations." (PMID 35216474, 2022). "For example, sirolimus (rapamycin) has been demonstrated to be an effective agent in the treatment of lymphatic malformations by targeting the PIK3CA pathway, which is activated in the endothelial cells of these lesions." (PMID 36198763, 2022).
lymphatic malformation (continued). "We identified somatic variants within 26 of 44 (59%) individuals with slow-flow anomalies (either lymphatic malformation, venous malformation (VM), or mixed lymphatic/venous malformations) within the genes PIK3CA, TEK, GNAQ, BRAF, GNA11, and PIK3R1 with VAFs ranging between 0.7% to 24.8%." (PMID 39669602, 2024). "PIK3CA mutations in lymphatic malformation may stimulate the expression of VEGF-C or VEGFR3, induce the binding of PIK3CA to the cellular membrane, or increase cell proliferation, chemotaxis, and angiogenesis through the activation of downstream Akt/mTOR." (PMID 35216474, 2022). "Abnormal capillary dilation may occur via the same mechanism as indicated for venous or lymphatic malformations through PIK3CA/Akt/mTOR." (PMID 35216474, 2022). "Most patients with an common or combined lymphatic malformation with or without overgrowth harbour a somatic PIK3CA mutation." (PMID 34112235, 2021). "This is in contrast to cutaneous lymphatic malformations, where the related lymphangiogenic growth factor VEGFC is essential for Pik3ca-driven vessel overgrowth." (PMID 40410415, 2025). "Activating mutations in PIK3CA which encodes the phosphatidylinositol-4,5-bisphosphate 3-kinase catalytic subunit alpha cause VM without a TEK mutation and isolated lymphatic malformations (LM)." (PMID 37658401, 2023).
clear cell carcinoma (29 papers, 2013 to 2026). "The activating mutations in PIK3CA are common in clear cell carcinoma and relatively rare in the other histological subtypes." (PMID 38420012, 2024). "Studies have found that mutations in the gene encoding PI3K p110α, PIK3CA, are found in nearly 33% of clear-cell carcinoma cases, with the region of 3q26 having increased copy numbers in about 7 out of 9 established OvCa lines." (PMID 31284467, 2019). "Clear cell carcinoma frequently has both PIK3CA mutation (oncogene) and ARID1A mutation (tumor suppressor gene)." (PMID 30971221, 2019). "ARID1A and PIK3CA mutations were particularly important in the clear cell carcinoma subtype of EAOC." (PMID 29743986, 2018). "ID8 cells also lack other mutations typical of clear cell carcinoma (Arid1a, Pik3ca), low-grade serous carcinoma (Braf), endometrioid (Ctnnb1), or mucinous (Kras) carcinomas." (PMID 29927933, 2018). "Exon 9 and 20 of the PIK3CA gene were analyzed for clear cell adenocarcinoma, it was found that somatic mutations of PIK3CA gene was detected in 10/23(43%) and in all cases the type of mutation was H1047R in the kinase domain." (PMID 23768168, 2013). "Findings suggest that mutation of PIK3CA gene occur in putative pre cursor lesion of CCA ( Clear cell adenocarcinoma)." (PMID 23768168, 2013). "The clear cell carcinoma case presented with additional PIK3CA missense mutation." (PMID 35328131, 2022). "PIK3CA-activating mutations occur in 20% of endometrioid and clear-cell carcinomas." (PMID 31284467, 2019). "Furthermore, somatic mutation of the PI3K gene (PIK3CA) has been reported in 20% of endometrioid and clear cell carcinomas." (PMID 24868556, 2014). "Both PIK3CA mutation and CTNNB1 mutation were also significantly associated with endometrioid and clear cell carcinoma." (PMID 34615547, 2021). "For example, usually, low-grade serous carcinoma has ERBB2, BRAF and KRAS mutations, mucinous carcinoma has KRAS mutation, clear cell carcinoma has ARIDIA and PIK3CA mutations, and endometrioid cell carcinoma has CTNNB1, PTEN and PIK3CA mutations." (PMID 34041032, 2021). "A subset of clear cell carcinomas also harbored alterations in PIK3CA/PTEN/AKT pathway, particularly PTEN, indicating a potential benefit of PI3K/Akt/mTOR inhibitors." (PMID 32279409, 2020). "The JHOC-5 clear cell carcinoma cell line bears the tumor suppressor gene ARID1A (encoding BAF250) and PIK3CA mutations, which cooperate to promote tumor growth through IL-6 overproduction." (PMID 29930760, 2018). "On the other hand, clear cell carcinoma’s relatively better prognosis may be linked to its distinct molecular profile, characterized by frequent ARID1A and PIK3CA mutations, which could offer actionable therapeutic targets." (PMID 40095664, 2025). "Notably, clear cell carcinomas were marked by high prevalence of PI3KCA and ARID1A mutations (67% and 50% for PIK3CA and ARID1A, respectively), compared to HGSC and other EOC types (P = 1.067 × 10−05 and P = 5.43 × 10−04)." (PMID 31771620, 2019). "Our case, in which increased AKT phosphorylation was induced by loss of ARID1A rather than by PIK3CA mutation, could have resulted in clear cell carcinoma if not treated." (PMID 41574315, 2026). "Clear cell carcinomas were examined in 20.7% (n = 333) of the cases, with genomic alterations in ARID1A (n = 231, 69.4%) and PIK3CA (n = 190, 57.1%), consistent with previous reports." (PMID 38201563, 2023).
clear cell carcinoma (continued). "The observed alterations in clear cell carcinomas may be clinically relevant given that the Food and Drug Administration (FDA) has recently approved a PIK3CA inhibitor Piqray (alpelisib) combined with fulvestrant for the treatment of ER+/PIK3CA‐mutated metastatic breast carcinomas." (PMID 32279409, 2020). "PIK3CA expression was not related to clinical features or survival of clear cell carcinoma." (PMID 29743986, 2018).